RAMP1 (receptor activity modifying protein 1)
Description:
Accessory protein that interacts with and modulates the function of G protein-coupled receptors including calcitonin gene-related peptide type 1 receptor (CALCRL) and calcitonin receptor (CALCR). Required for the transport of CALCRL to the plasma membrane. Together with CALCRL, form the receptor complex for the calcitonin gene-related peptides CGRP1/CALCA and CGRP2/CALCB. Together with CALCR, form the AMYR1 receptor complex for amylin/IAPP and CGRP1/CALCA.
Tractability: Small molecule: an approved drug acts on it; a structure with a bound ligand is known; a high-quality ligand is known; it belongs to a druggable protein family. Antibody: UniProt places it where antibodies can reach, with high confidence; its Gene Ontology location is reachable by antibodies, with high confidence; UniProt predicts a signal peptide or a membrane-spanning region. Other modalities: a drug acting on it is in phase 2 or 3 trials.
Gene: Protein-coding gene on chromosome 2 (237,858,893 to 237,912,111, forward strand). Ensembl gene ENSG00000132329.
Subcellular location: Cell membrane
Subcellular location (Human Protein Atlas): Nuclear membrane; Nucleoplasm
Pathways (Reactome):
Signal Transduction: Calcitonin-like ligand receptors; G alpha (s) signalling events
Gene Ontology:
Molecular function: amylin receptor activity; calcitonin gene-related peptide binding; calcitonin gene-related peptide receptor activity; coreceptor activity; protein binding
Biological process: adenylate cyclase-activating G protein-coupled receptor signaling pathway; amylin receptor 1 signaling pathway; amylin receptor signaling pathway; angiogenesis; calcitonin gene-related peptide receptor signaling pathway; calcium ion transport; positive regulation of glycoprotein biosynthetic process; protein localization to plasma membrane; protein transport; receptor internalization; cellular response to hormone stimulus; G protein-coupled receptor signaling pathway; intracellular protein transport; regulation of G protein-coupled receptor signaling pathway
Cellular component: cell surface; CGRP receptor complex; plasma membrane; receptor complex; membrane
Genetic constraint (gnomAD): Loss-of-function variants: 9 observed, 8.61 expected, observed/expected ratio (o/e) 1.05, 90% interval 0.63 to 1.73. That is too few expected variants to judge how well the gene tolerates losing a copy. Missense variants: 192 observed, 203.97 expected, observed/expected ratio (o/e) 0.94, 90% interval 0.84 to 1.06. Synonymous variants: 92 observed, 85.14 expected, observed/expected ratio (o/e) 1.08, 90% interval 0.91 to 1.28.
Homologues: Orthologues: chimpanzee RAMP1 (98% identical), macaque RAMP1 (95% identical), dog RAMP1 (72% identical), guinea pig RAMP1 (72% identical), mouse Ramp1 (71% identical), pig RAMP1 (68% identical), tropical clawed frog ramp1 (49% identical), zebrafish ramp1 (48% identical). Paralogues in human: RAMP3 (30% identical), RAMP2 (29% identical).
Diseases named in the same sentence as RAMP1 in open-access papers:
RAMP1 is named in the same sentence as 63 diseases in open-access papers, as found by Europe PMC text mining. Sharing a sentence is not in itself a finding about the gene and the disease. The quoted sentences say what the papers report.
migraine (42 papers, 2014 to 2026). "The SNPs rs3754701 and rs7590387 of the gene encoding RAMP1 were associated with migraine in a genome-wide association study, but the results are unpublished." (PMID 40711166, 2025). "In fact, the genotype characterized by the rs7590387 G allele of the RAMP1 gene was associated with a lower probability of being a 75% responder to erenumab, i.e., a patient that shows a reduction in monthly migraine days ≥75%." (PMID 40711166, 2025). "A higher migraine risk was reported in females with a low level of DNA methylation in the gene encoding receptor activity modifying protein 1 (RAMP1), which is a key receptor unit of CGRP." (PMID 37199585, 2023). "Our aim in this study was to investigate the RAMP1 promoter methylation status in female migraineurs and controls in order to find epigenetic biomarkers that can predict migraine risk in an accessible body fluid, such as blood." (PMID 35624913, 2022). "Being lack of the exact mechanism of DNA methylation implicated in migraine, from the present data, it is difficult to interpret the differences of DNA methylation at RAMP1 gene promoter within migraine subgroups." (PMID 26501962, 2015). "Future research should investigate whether RAMP2 predominance over RAMP1 in the meningeal vasculature results in altered migraine susceptibility or in a different response to anti-migraine medication in these patients." (PMID 39390360, 2024). "Because our data demonstrates a full protection in systemic Ramp1-deficient animals and partial protection in lymphatic Calcrl-deficient animals, our findings indicate that migraine pathophysiology is multifactorial and that the MLVs are one of many CGRP target cells." (PMID 38743922, 2024). "The elevated expression of RAMP1 in female TG may indicate a potential involvement of RAMP1 in migraine susceptibility or pathogenesis in females." (PMID 39516766, 2024). "Still it is elusive that DNA methylation at RAMP1 promoter is associated with migraine." (PMID 26501962, 2015). "In this study, our aim is to explore whether methylation pattern at the promoter region of RAMP1 gene in peripheral leukocyte is associated with migraine using quantitative methylation approach." (PMID 26501962, 2015). "In an inflammatory soup model of migraine, there was an increase in expression of mRNAs encoding CGRP, RAMP1, RCP, and CLR in the trigeminal ganglia of males; however, only CLR and RCP levels were increased in females." (PMID 40708951, 2025). "This is in agreement with the current results where migraine induction using NTG resulted in a 2.3-fold increase in RAMP-1 gene expression." (PMID 39500819, 2025). "Factors such as the central nervous system, trigeminovascular system, blood–brain barrier (BBB), and Receptor Activity Modifying Protein 1, have been increasingly studied for their roles in the pathophysiological progression of migraine." (PMID 41404467, 2025). "The transdermal delivery of niosomal ZOL (TPFsp60/6−1:1) showed significantly enhanced management of migraine pain symptoms and markers, decreased RAMP-1, NPTX-2, and CB-1/MAPK gene expression reflecting improved efficacy and brain receptor delivery." (PMID 39500819, 2025). "In our study, ZOL significantly reduced RAMP-1 mean gene expression in the brains of rats with NTG-induced migraine by 23% compared to untreated rats." (PMID 39500819, 2025). "The CALCA and RAMP1 genes encode calcitonin-gene-related peptide (CGRP), which is an important factor involved in migraine pathogenesis." (PMID 40391079, 2025). "Novel mechanisms were proven to be exerted by ZOL in ameliorating migraine headache and pain such as decreasing the gene expression of key epigenetically altered genes in migraine; RAMP-1 and NPTX-2, and modulation of the endocannabinoid; CB-1/MAPK pathway." (PMID 39500819, 2025).
migraine (continued). "They studied light aversive behavior in migraine by using a transgenic mouse line (nestin/hRAMP1), which upregulates the receptor protein RAMP1, a subunit of the CGRP receptor required for CGRP binding." (PMID 40708951, 2025). "OPRM1 emerges as a pivotal hub, instigating the activation of GNAS and GNB1, subsequently influencing proteins such as RAMP1, RAMP2, RAMP3, CALCB, CALCR, and SLC5A2 all implicated in migraine attacks." (PMID 39215033, 2024). "Nestin/RAMP1 transgenic mice, for example, that over-express human RAMP1 in the central nervous system show some migraine-typical features, such as photophobia and allodynia, after CGRP administration." (PMID 37298078, 2023). "It has also been reported that CGRP-sensitized mice overexpressing RAMP1 show aversion to light, similarly to photophobia, which is a well-known migraine symptom." (PMID 35624913, 2022). "To date, only one other study has analyzed the methylation of the human RAMP1 gene promoter in the context of migraine." (PMID 35624913, 2022). "In this study, the positive expression, mRNA expression, and protein expression of TRPV1, CGRP, CRLR, and RAMP1 in the trigeminal nerve of migraine model rats significantly increased." (PMID 35350752, 2022). "This is important for CGRP family receptors as migraine targets, but also other GPCRs which interact with RAMP1." (PMID 36555690, 2022). "Recently, RAMP1 signalling has been clinically targeted by antagonists for the treatment of migraines." (PMID 32869443, 2020). "The neuropeptide CGRP, acting through the G-protein coupled receptor CALCRL and its coreceptor RAMP1, plays a key role in migraines, which has led to the clinical development of several inhibitory compounds." (PMID 31756985, 2019). "Sex-specific difference in mRNA levels of RAMP1 have been observed in rat migraine model, as also have been found in the light-aversion behavior in transgenic hu-RAMP1 mice." (PMID 26501962, 2015). "The Nestin/RAMP1 transgenic mice, over-expressed human RAMP1 in central neurological system (CNS), can mimic some features of migraine, such as photophobia and allodynia, when intracerebroentricular administration of CGRP." (PMID 26501962, 2015). "Receptor activity modifying protein 1(RAMP1) is a key receptor subunit of calcitonin gene related peptide (CGRP) playing a critical role in migraine." (PMID 26501962, 2015). "Receptor activity modifying protein 1 (RAMP1) is a key receptor subunit of calcitonin gene related peptide (CGRP), which functions as an important neural transmitter implicated in migraine." (PMID 26501962, 2015). "Although at the promoter region of RAMP1, these sequences contain a number of CpG dinucleotides, few attempts are to investigate the relationship between DNA methylation of RAMP1 gene and migraine." (PMID 26501962, 2015). "Recent data have demonstrated a close transcriptional relationship between oestrogen and calcitonin gene-related peptide (CGRP), as well as the receptor component “receptor activity-modifying protein 1” (RAMP1), in migraine pathology and current successful treatments." (PMID 41680623, 2026). "Thus, CGRP selective antagonists that recognize RAMP-1 epitopes were developed and tested for migraine treatment as promising candidates to regulate the number of functional CGRP receptors." (PMID 39500819, 2025). "Epigenome alteration may lead to the progression to chronic migraine (chronification of migraine), such as the altered methylation pattern of the receptor activity-modifying protein-1 (RAMP-1), and the neuronal pentraxin-2 (NPTX-2) genes." (PMID 39500819, 2025). "Key epigenetically altered genes in migraine include RAMP-1 and NPTX-2 genes." (PMID 39500819, 2025). "The patch was finally examined in vivo to investigate possible novel mechanisms for the antimigraine action of ZOL via alternative pathways affecting the altered migraine chronification genes (RAMP-1, and NPTX-2), or microRNAs and modulation of the endocannabinoid; CB-1/MAPK pathway." (PMID 39500819, 2025).
migraine (continued). "NTG thus induced CLR/RAMP1–dependent migraine-like responses." (PMID 39087472, 2024). "In contrast, adrenomedullin receptors 1 and 2 (AM1/2) that express CLR but not RAMP1 have not been implicated in inducing migraine." (PMID 38658853, 2024). "Since the first Food and Drug Administration (FDA) approval of G-protein-coupled receptor (GPCR)-directed antibody against RAMP1-CLR for the treatment of migraine in 2018, the involvement of the RAMP1-CLR signaling axis in peripheral neurons has gained significant attention in recent years." (PMID 37796823, 2023). "Previous studies have indicated that DNA methylation at the RAMP1 promoter may play a role in migraines, with a low level of methylation at CpG units potentially serving as a risk factor for females." (PMID 37796823, 2023). "Therefore, the RAMP1 subunit is a critical and defining constituent of two migraine-relevant receptors." (PMID 36555690, 2022). "A relevant role for RAMP1 in migraine pathology has been shown in several studies." (PMID 35624913, 2022). "This CpG may potentially play a role in migraine, affecting RAMP1 transcription or receptor malfunctioning and/or altered CGRP binding." (PMID 35624913, 2022). "This study provides the first evidence that DNA methylation at RAMP1 promoter might play a role in migraine." (PMID 26501962, 2015). "These suggested RAMP1 would have a potential role in migraine." (PMID 26501962, 2015). "Several transgenic and expression studies also demonstrate that RAMP1 is involved in migraine." (PMID 26501962, 2015). "Additionally, epigenetic regulation – particularly the involvement of CALCA and RAMP1, which encode CGRP and its receptor – suggests that gasotransmitter interactions may have broader implications for migraine heritability and chronicity." (PMID 40391079, 2025). "Interestingly, sex-specific differences in RAMP1 mRNA level were observed in a rat migraine model." (PMID 35682830, 2022). "Clinical observations reveal that injection of CGRP could introduce a delayed migraine-like headache in migraineurs, but not in migraine-free controls, which indicates the regulation of RAMP1 gene could been implicated in migraine susceptibility." (PMID 26501962, 2015). "However, genetic polymorphism studies and genome-wide associated studies failed to link migraine with variations in RAMP1 gene." (PMID 26501962, 2015). "We hypothesized that epigenetic modulation could participate in the pathological mechanism of migraine, and expected that differential DNA methylation of RAMP1 in leukocytes could provide potential epigenetic biomarkers for the identification and diagnosis of migraine." (PMID 26501962, 2015). "In spite of this, the clinical benefits of gepants are very similar, suggesting that CGRP signaling promoting migraine likely requires interactions with both CLR and RAMP1." (PMID 38658853, 2024). "This partial reduction of chronic migraine symptoms correlates with our observations of approximately 50% attenuation of migraine symptoms in mice with impaired lymphatic response to CGRP compared with the total prevention, as observed in Ramp1–/– mice." (PMID 38743922, 2024). "Mapping the anatomical localization of RAMP1, a component of both the CGRP and AMY1 receptors, in migraine-relevant tissues is important for CGRP-related research." (PMID 36555690, 2022). "Receptor activity modifying protein (RAMP1) is part of the Calcitonin Gene-Related Peptide (CGRP) receptor, a pharmacological target for migraine." (PMID 35624913, 2022). "The RAMP1 protein is a key receptor subunit of the calcitonin gene related peptide (CGRP), and both are expressed in trigeminal neurons and are essential for migraine pathogenesis." (PMID 31739474, 2019). "A possible effect of amylin and adrenomedullin on the RAMP1/CLR, or of CGRP on the different combinations of receptors for amylin and adrenomedullin has been claimed to contribute to the pro-migraine action of CGRP or its receptor." (PMID 30764776, 2019).
migraine (continued). "CGRP plays an important role in migraine pathophysiology and localization of CGRP and its receptors (CLR and RAMP1) has already been described in TNC and C1 region of the spinal cord." (PMID 28337634, 2017). "Demographics, migraine history, comorbidities, treatment outcomes, and genetic variants in CGRP receptor-related genes (CALCRL and RAMP1) were evaluated for associations with non-response to ERE, defined as a <50% reduction in monthly migraine days." (PMID 41464829, 2025). "Upregulation of RAMP1 expression increases CGRP sensitivity in the trigeminal ganglia, which could have implications for migraine." (PMID 40708951, 2025). "Evidence suggests that alterations in the DNA methylation patterns of genes related to migraines, including calcitonin gene-related peptide alpha (CALCA) and receptor activity modifying protein 1 (RAMP1), result in aberrant protein expression, ultimately contributing to migraine." (PMID 40391079, 2025). "The co-localization of CLR and RAMP1 on Aδ-fibers with CASPR suggests a potential role for this receptor in modulating trigeminal nerve function and neuronal excitability, with implications for migraine pathophysiology." (PMID 39516766, 2024). "The novel anti-migraine drugs targeting the canonical CGRP receptor (i.e. gepants and the monoclonal antibody erenumab) are designed to target the hydrophobic pocket between CLR and RAMP1, thereby preventing direct binding of CGRP to the receptor." (PMID 39390360, 2024). "RAMP1 belongs to the receptor activity-modifying protein (RAMP) family, best known for its role in modulating the activity of the calcitonin receptor (CLR), which has significant implications in the treatment of migraines." (PMID 39188714, 2024). "Receptor activity-modifying protein 1 (RAMP1), a type I transmembrane domain protein, binds the calcitonin receptor-like receptor (CLR) class B GPCR to form the Calcitonin gene-related peptide (CGRP) receptor which is involved in the pathology of migraine." (PMID 37039481, 2023). "CGRP and the molecular subunits of the canonical CGRP receptor, the calcitonin receptor-like receptor (CLR) and receptor activity-modifying protein 1 (RAMP1), are all expressed within the TG where they may contribute to migraine pathogenesis." (PMID 35620595, 2022). "One migraine treatment target that has attracted great attention is the calcitonin gene-related peptide (CGRP)-mediated CLR/RAMP1 receptor (i.e., the calcitonin receptor-like receptor (CLR) and receptor activity-modifying protein 1 (RAMP1) complex) signaling." (PMID 36569288, 2022). "The presence of extensive high-affinity CGRP binding sites in discrete locations throughout the brain, including migraine-relevant regions such as the brainstem, implies that RAMP1 is present but does not directly demonstrate this." (PMID 36555690, 2022). "Walker and colleagues showed the presence of CTR, and furthermore, they suggested that the AMY1 receptor (CTR/RAMP1) could be a relevant target for CGRP and perhaps a novel way in migraine therapy." (PMID 32086679, 2020). "The co-localization of CLR and RAMP1 on the Aδ-fibers with CASPR suggest a potential role for these receptors in modulating trigeminal nerve function and neuronal excitability, which could have important implications for understanding migraine pathophysiology." (PMID 39516766, 2024). "Interestingly, the observations in the current study showing two types of expression patterns of RAMP1 and RAMP2 in HMMA donors, could suggest that also two types of (migraine) patients exist, who possibly respond differently to treatment." (PMID 39390360, 2024). "Additionally, the co-localization of CLR and RAMP1 on Aδ-fibers with CASPR suggests a potential role for these receptors in modulating trigeminal nerve function and neuronal excitability, with implications for migraine pathophysiology." (PMID 39516766, 2024).